TNF (tumor necrosis factor)
Diseases named in the same sentence as TNF in open-access papers (continued):
Sharing a sentence is not in itself a finding about the gene and the disease.
Sepsis (continued). "An increase in tumor necrosis factor (TNF)-α and interleukin (IL)-1β contributes to cardiac dysfunction during sepsis in humans and has been directly linked to Toll-like receptor (TLR) signaling." (PMID 24171786, 2013). "Our results showed that rs1800629 (−308G/A), located in the promoter region of TNF, was associated with significantly increased risk for severe sepsis." (PMID 23029405, 2012). "The most widely studied polymorphism is associated with overproduction of TNF-α; which has been related to a 2.1–13 fold increase in the incidence of severe sepsis from all causes including pneumonia." (PMID 22916119, 2012). "Our results provided evidence that rs1800629, a functional SNP in the promoter region of TNF, was significantly associated with susceptibility to severe sepsis in Chinese Han population." (PMID 23029405, 2012). "Due to its pivotal position in the inflammatory and coagulation systems that are known to cause the demise in sepsis, TNF-α has been targeted as a treatment of sepsis in many clinical trials." (PMID 23251827, 2012). "Our results showed that rs1800629, a SNP in the promoter region of TNF, was significantly associated with risk for severe sepsis." (PMID 23029405, 2012). "TNF-α is an important proinflammatory cytokine and it has been implicated in the pathogenesis of many inflammatory and autoimmune diseases such as sepsis, inflammatory intestinal disease and RA." (PMID 22472022, 2012). "Our results showed that rs1800629A allele was associated with higher TNF-α serum concentrations on the first day of severe sepsis." (PMID 23029405, 2012). "Sepsis-associated encephalopathy, observed in critically ill septic patients, has been associated with increased tumor necrosis factor (TNF-alpha)." (PMID 21666785, 2011). "This further underlines that IL-6 & TNF-α are involved in the pathogenesis of sepsis but that they cannot be considered independent markers, based on our analyses." (PMID 22220196, 2011). "The direct pulmonary insult (acid instillation) was associated with a greater increase in plasma IL-6 and TNF-α concentrations, but the indirect pulmonary insult (sepsis) resulted in increased plasma ICAM-1 concentrations." (PMID 22204611, 2011). "TNFα is known to increase the activity of the canonical NFκB pathway in conditions associated with muscle weakness, including sepsis, cancer, and ageing and to cause protein degradation in cultured myotubes." (PMID 21843349, 2011). "Our results showed that a tag SNP rs5743867 in TOLLIP, which influences the expression of TOLLIP mRNA and the production of TNF-α and IL-6, was significantly associated with susceptibility to sepsis." (PMID 21219635, 2011). "An association with sepsis severity and outcome following different inflammatory insults was found repeatedly, with a tendency towards increasing levels of TNFα and therefore a stronger inflammatory response." (PMID 21274447, 2010). "An early imbalance of IL-10 in sepsis was shown to be associated with death despite TNFα production." (PMID 20076757, 2010). "Elevated plasma concentrations of TNFα have been associated with poor prognosis in sepsis, but also in patients with leptospirosis." (PMID 20076757, 2010). "In contrast, dysregulation in TNFα production or signaling has been associated with a wide range of inflammatory disorders, ranging from sepsis to anaphylaxis to autoimmune diseases." (PMID 20463923, 2010). "The peritonitis-induced sepsis caused a significant fall of arterial pH and markedly increased plasma levels of TNF-α and IL-6." (PMID 19108740, 2008). "Logistic regression revealed that among the seven candidate risk factors (admission plasma gelsolin, IL-6, IL-10, TNF-α, albumin, age and sex), admission plasma gelsolin was the only independent factor able to predict the occurrence of severe sepsis." (PMID 18706105, 2008). "Demographic data and genotype frequencies of TNF and IL-10 polymorphisms in patients with sepsis and controls." (PMID 16859504, 2006).
Sepsis (continued). "In a model of experimental sepsis by Escherichia coli, thalidomide was proved very effective in reducing serum levels of TNFα, a phenomenon that was associated with refraining of evolution to sepsis." (PMID 15978135, 2005). "Our study demonstrates that the TNF-α (−238, rs361525) GA/AA genotypes could predispose critically ill neonates with sepsis to the development of AKI." (PMID 40724987, 2025). "IL-1β and TNF-α are major inflammatory cytokines involved in the acute inflammatory response, and higher levels are associated with an increased risk of postoperative infection, systemic inflammatory response syndrome, and sepsis." (PMID 40142333, 2025). "The use of anti-TNF agents has been shown to increase the mortality rate associated with sepsis." (PMID 40699834, 2025). "Therefore, markers such as white blood cell count, C-reactive protein, tumor necrosis factor, IL-1, and IL-6 are commonly used as auxiliary diagnostic indicators for sepsis in clinical practice." (PMID 40540505, 2025). "Targeting the TNFα–necroptosis axis and enhancing endogenous H2S production may represent novel therapeutic strategies for sepsis-associated adrenal dysfunction." (PMID 40430756, 2025). "Additionally, due to the limited availability of patient sera, we were unable to detect other biomarkers associated with sepsis, such as TNF-α, IL-1β, and IL-8." (PMID 40176879, 2025). "When these factors were simultaneously included in the generalized estimating equation along with baseline data that showed significant differences, we found that only urinary DS and plasma TNF-α were independently associated with ARDS onset in sepsis patients." (PMID 40404729, 2025). "In the central nervous system, agents like exedin-4 and liraglutide reduce neuroinflammation by inhibiting microglial activation and cytokine production (IL-1β, IL-6, TNF-α), while preserving neuronal integrity and preventing cognitive dysfunction associated with sepsis." (PMID 41357527, 2025). "Glu level (OR = 1.117, 95% CI = 1.032–1.210, P = 0.006), TBA (OR = 2.898, 95% CI = 1.946–4.315, P = 0.000), PCT (OR = 1.004, 95% CI = 1.001–1.008, P = 0.005) and TNF-α (OR = 1.091,95% CI = 1.011, 1.177) were independent prognostic risk factors for pediatric sepsis." (PMID 39266629, 2025). "Furthermore, macrophages play a crucial role in the liver damage caused by elevated levels of IL-1β and TNF-α both in the liver and serum of LPS-induced sepsis mice." (PMID 40298842, 2025). "Specifically, we have demonstrated that LBT exerts significant reductions in TNF-α, IL-6, and IL-1β levels while mitigating LPS-induced sepsis through the inhibition of genes associated with bacterial infection, cellular response to lipopolysaccharide, and cytokine-cytokine receptor interaction." (PMID 38799158, 2024). "For example, TNF-α and IL-1β are typically associated with the early, hyperinflammatory phase of sepsis, while IL-17 may be more involved in the later, immunosuppressive phase." (PMID 39205680, 2024). "Lastly, newborns carrying the TNF-α–308 A allele (P = 0.016,OR = 1.257, 95% CI: 1.044–1.513)or the AA genotype(P = 0.009,OR = 1.913, 95% CI: 1.179–3.10) have a significantly increased risk of sepsis." (PMID 38848433, 2024). "For example, the TNF-α + 489G/A SNP A allele may protect against sepsis-related mortality within 24 h after the onset of sepsis." (PMID 38716051, 2024). "Elevated circulating levels of cytokines such as TNF-α, IL-1β, IL-6, IL-8, and IL-10 have been linked to increased morbidity and mortality in patients with sepsis, suggesting that their removal could be beneficial for treatment." (PMID 39766623, 2024).
Sepsis (continued). "Although the precise role of CD160 in sepsis remains elusive, it has been implicated in fostering an amplified inflammatory response through its association with heightened cytokine secretion from NK cells, encompassing TNF-alpha, IFN-gamma, and IL-614." (PMID 38263335, 2024). "Elevated TNF-α concentration was associated with increased 28-day sepsis mortality." (PMID 38558800, 2024). "However, it should be noted that HLA-DR downregulation correlates with reduced TNF, IL-6, and IL-1β release post- lipopolysaccharide (LPS) stimulation, increasing the risk of adverse events and death in sepsis." (PMID 38474403, 2024). "Polymorphisms on cytokine genes (i.e., TNF-alpha 1-2 alleles and IL-1Ra 1-2 alleles) have their impact on the course of sepsis, showing an increased severity of the infection in TNF2 carriers and in IL-1Ra2 (associated with higher levels of IL-1 and lower levels of IL-1Ra)." (PMID 39768405, 2024). "Furthermore, thermal-burn patients with a combination of elevated IL-6 and IL-12p70 concentration and decreased TNF-α at admission were found to be at a greater risk of developing and dying of sepsis." (PMID 39716257, 2024). "To test whether acute and systemic inflammation in mice might affect extracellular pT73-Rab10 to total Rab10 ratios, we introduced a polymicrobial sepsis challenge to outbred CD-1 mice that caused large increases in serum concentrations of IFNγ and TNF." (PMID 38862989, 2024). "Additionally, it decreased proinflammatory cytokine levels (TNF-α and IL-6), reducing the risk of sepsis from rapid bacterial lysis." (PMID 38622637, 2024). "Moreover, we found that serum levels of IL-6 and TNF-α were significantly higher in patients with septic shock compared to those with sepsis (Fig. EV4H), suggesting that IL-6 and TNF-α are closely associated with the progression of sepsis." (PMID 39294473, 2024). "Similarly, we have validated here the ameliorating effect of amisulpride in the acute LPS-induced model of sepsis and, importantly, in the TNFΔΑRE mouse model of chronic arthritis, where the pathogenic source of TNF lies with the bone marrow compartment." (PMID 37014697, 2023). "Hyperferritinemia and MCP-1/CCL2 were also causally associated with reduced ex vivo whole blood TNF response to endotoxin implying that targeting hyperferritinemic sepsis and macrophage activation could also improve infection clearance." (PMID 37674218, 2023). "Measurement of other cytokines, such as TNF-alpha or IL-1, could be more suitable for sepsis-associated hyperinflammation." (PMID 37596304, 2023). "The levels of proinflammatory cytokines including IL-6, IL-1β, Il-17A and TNF-α, as detected by quantitative PCR or enzyme-linked immunosorbent assay (ELISA), were decreased in lung tissue of sepsis mice upon treatment of JHD, as compared with their counterpart with no treatment." (PMID 37081964, 2023). "Inflammatory hallmark cytokines IL-1β, IL-6, and TNF-α constitute the cytokine storm during sepsis." (PMID 38152336, 2023). "Subsequently, Wang and colleagues demonstrated a role for HMGB1 in sepsis, although it has also been reported to participate in the transcriptional regulation of cancer-related genes such as tumor necrosis factor alpha, E-selectin, breast cancer type 1 susceptibility protein, and insulin receptor." (PMID 37009887, 2023). "In addition, IL-10 levels are important because of the role of the anti-inflammatory IL-10 by inhibiting the expression of pro-inflammatory mediators such as TNF-α and IL-1β, and by conferring diminished resistance to pathogenic organisms during sepsis." (PMID 38235139, 2023). "A total of 15% of hospitalized patients with a poor clinical outcome were associated with the rs1800629 polymorphism of TNF-α that is strongly correlated with sepsis, while 6.7% of patients were associated with a less severe form of CAP, due to the rs1799752 I/I genotype of ACE." (PMID 37630611, 2023).
Sepsis (continued). "In addition, an increased number of neutrophils in the lungs and increased levels of pro-inflammatory cytokines such as IL-1β and TNFα in the serum is commonly observed during sepsis and, is associated with cardiac failure and death." (PMID 37624851, 2023). "Researchers have proposed that VEGF may sensitize endothelial cells to the effects of low concentrations of TNF-α, contributing to the increased permeability of endothelial cells—a phenomenon that may be linked to the higher mortality observed in sepsis cases." (PMID 38313162, 2023). "Moreover, the MHC class II molecule HLA-DR was reduced, which is also reduced on monocytes from sepsis patients where it was linked to a reduction in TNF-α response." (PMID 36961624, 2023). "Human chorionic gonadotropin, a hormone first identified in the placenta, can reduce the expression of pro-inflammatory mediators (TNF-α, IL-6, and Pentraxin 3) and chemokines (macrophage inflammatory protein 1-a and chemotokine ligand 5) caused by sepsis, and improve organ damage caused by sepsis." (PMID 37629199, 2023). "Macrophages can recognize LPS released by Gram-negative bacteria through TLRs, leading to excessive expression of inflammatory factors, including IL-1β, TNF-α, and IL-6, which are considered the leading cause of multiple organ dysfunction in the early stage of sepsis." (PMID 37840694, 2023). "TNF-α is crucial to the hypothermia and lethality associated with sepsis in mice." (PMID 36808423, 2023). "TNFα blockade prevents endotoxic- and bacteremia-induced shock and attenuates metabolic acidosis and pulmonary dysfunction in sepsis, the most significant events associated with sepsis." (PMID 37520526, 2023). "Our results show that not only the systematic Slc38a6 knock-out but also Slc38a6 specific knock-out in LyzCRE cells could ameliorate LPS induced sepsis-associated pulmonary inflammation severity, and decrease inflammatory cytokines, such as TNF-α and IL-1β." (PMID 36707853, 2023). "TNF-α and IL-6 are critical pro-inflammatory cytokines in sepsis due to their consistent association with the severity, mortality and organ dysfunction of patients with sepsis." (PMID 35167625, 2022). "In line with this, the experimental results from ELISA analysis underlined that sepsis might lead to inflammatory response by elevating the levels of TNF-α, IL-6, IL-1β and IL-18." (PMID 35264055, 2022). "The cytokine storm, a key feature of sepsis that has been linked to increased risk of mortality, is characterised by a life-threatening systemic inflammation caused by high circulating levels of the proinflammatory cytokines TNF-α, IL-6, and IL-1β." (PMID 35625756, 2022). "TNF-α causes fatal toxicity when overexpressed, causing sepsis and skin inflammation." (PMID 36616208, 2022). "In a previous study, an increase in TNF-α in the group treated with the BCP-DHA combination was found in the sepsis model, which may be related to its susceptibility to stimulation by COX inhibitors." (PMID 36357780, 2022). "In addition to sepsis and upregulation of pro-inflammatory cytokine (IL-6, IL-1ß, and TNF-α) production, the association of miR-192-5p with regulation of the miR-192-5p–X-linked inhibitor of apoptosis axis in this condition has been investigated in animals." (PMID 35305556, 2022). "Importantly, cecal ligature and puncture (CLP) in rodents does reproduce clinical sepsis-associated hemodynamic phases and results in increased cerebrospinal fluid concentrations and brain expression of IL-1beta and TNF-alpha." (PMID 35215252, 2022). "Macrophages are activated under the stimulation of cytokines in sepsis such as macrophage colony-stimulating factors, TNF-α, pathogenic microorganisms and chemical mediators, and then the activated macrophages phagocytize and kill a variety of pathogens and present antigens." (PMID 35923893, 2022).
Sepsis (continued). "In a polymicrobial sepsis model, sNASP-mutant mice had defective bacterial clearance from the lungs due to marked reductions in IL-1β, TNF-α, and IFN-γ production associated with poor adhesion molecule expression and leukocyte recruitment, and defective phagolysosome formation." (PMID 35386914, 2022). "In murine models of LPS-induced sepsis and bacterial sepsis, B-1 cell-deficient mice showed exacerbated sepsis severity and increased mortality, accompanied by increased levels of proinflammatory cytokines TNF-α and IL-6 and decreased levels of IL-10 in the plasma, lung, and gut." (PMID 36425582, 2022). "High TNF‐α levels are associated with mortality in patients with sepsis." (PMID 36444621, 2022). "Additionally, elevated ratios of anti-inflammatory and pro-inflammatory cytokines (e.g., IL-10/TNF) are proposed markers of sepsis-induced immunosuppression and are associated with multiple organ failure." (PMID 35685286, 2022). "Indeed, therapies targeting TNF-α for conditions such as sepsis and autoimmune disorders can increase host susceptibility to infection and have a negative outcome." (PMID 35587473, 2022). "Four cytokines, TNF-α, IL-1β, IL-6, and IL-8 have been most strongly associated with sepsis." (PMID 35563475, 2022). "However, the TNF SNP functional gene rs1800629 was strongly associated with susceptibility to sepsis." (PMID 36358327, 2022). "The results showed that when PCT ≥ 6.67 and TNF-α ≥ 39.4, they could be used as predictors of the risk of sepsis." (PMID 34745113, 2021). "If so, RIPK3 might be a beneficial therapeutic target in vascular diseases associated with high TNFα levels such as sepsis." (PMID 34153072, 2021). "We examined whether the sepsis-associated inflammatory stimuli lipopolysaccharide (LPS) and TNF-α regulate the expression of GSEC and PFKFB3 mRNA in neutrophils in vitro." (PMID 34907156, 2021). "They found that the chimeric mouse harboring ADAM17-deficient leukocytes had longer survival after Escherichia coli-mediated peritoneal sepsis, which was associated with a reduction in systemic proinflammatory cytokine levels, including TNF, and bacterial burden." (PMID 33579029, 2021). "Sepsis was independently associated with higher serum IL-18 and TNF levels in two-time-point GEE models (before and at the end of SBT) adjusted for APACHE II score and age, with beta coefficients (95% CI, p values) as follows: IL-18 388 (53—723, p = 0.023), and TNF 32 (0.3—64, p = 0.048)." (PMID 35054259, 2021). "Reduced regional blood flow in the brain in rats exposed to LPS, to model septicaemia that resulted in microglial activation and neuronal loss, was associated with enhanced transcription of several cytokines and chemokines including TNF-α, IL-1β, TGF-β and MCP-1 within the brain." (PMID 33723589, 2021). "In accordance with our current findings, however, extracellular ATP may also induce P2Y11 receptor‐mediated suppression of TNF‐α and thus establish the sepsis‐associated hyporesponsive state." (PMID 33463722, 2021). "During sepsis, pathogen-associated molecular patterns and damage-associated molecular patterns activate TLRs, which then trigger inflammation by stimulating the production and release of pro-inflammatory cytokines, specifically TNF-α and IL-1β." (PMID 34177611, 2021). "Moreover, in lung tissue derived from Dcn-deficient mice with sepsis, IL-10 levels were decreased and IL-12 and TNFα levels were increased." (PMID 34381449, 2021). "The lower TNF-α production in women than in men could be one of the factors causing the lower incidence of sepsis among women." (PMID 35011664, 2021). "In sepsis, a great amount of pro-inflammatory cytokines and damage associated molecular patterns (DAMPs) released, including tumor necrosis factor-α (TNF-α), interleukin (IL) family and high mobility group box 1 (HMGB1) which lead to further organ dysfunction and multiple cell death." (PMID 34867376, 2021).